IFNL2 (interferon lambda 2)
Description:
Cytokine with antiviral, antitumour and immunomodulatory activities. Plays a critical role in the antiviral host defense, predominantly in the epithelial tissues. Acts as a ligand for the heterodimeric class II cytokine receptor composed of IL10RB and IFNLR1, and receptor engagement leads to the activation of the JAK/STAT signaling pathway resulting in the expression of IFN-stimulated genes (ISG), which mediate the antiviral state. Has a restricted receptor distribution and therefore restricted targets: is primarily active in epithelial cells and this cell type-selective action is because of the epithelial cell-specific expression of its receptor IFNLR1. Seems not to be essential for early virus-activated host defense in vaginal infection, but plays an important role in Toll-like receptor (TLR)- induced antiviral defense. Plays a significant role in the antiviral immune defense in the intestinal epithelium. Exerts an immunomodulatory effect by up-regulating MHC class I antigen expression.
Synonyms: IL-28A; IL28A; IFNL2a; IFNL3a
Tractability: Antibody: UniProt places it where antibodies can reach, with high confidence; its Gene Ontology location is reachable by antibodies, with high confidence; UniProt predicts a signal peptide or a membrane-spanning region.
Gene: Protein-coding gene on chromosome 19 (39,268,396 to 39,270,188, forward strand). Ensembl gene ENSG00000183709.
Subcellular location: Secreted
Pathways (Reactome):
Immune System: Interleukin-20 family signaling
Gene Ontology:
Molecular function: signaling receptor binding; cytokine activity
Biological process: cellular response to virus; defense response to virus; innate immune response; mucosal immune response; type III interferon-mediated signaling pathway; cell surface receptor signaling pathway via JAK-STAT; positive regulation of immune response
Cellular component: extracellular region
Genetic constraint (gnomAD): Loss-of-function variants: 18 observed, 19.61 expected, observed/expected ratio (o/e) 0.92, 90% interval 0.63 to 1.36. The upper end of that interval is the gene's LOEUF score, 1.36, which puts it in group 5 of 6, group 1 being the genes least tolerant of losing a copy. Missense variants: 225 observed, 252.46 expected, observed/expected ratio (o/e) 0.89, 90% interval 0.8 to 1. Synonymous variants: 96 observed, 111.31 expected, observed/expected ratio (o/e) 0.86, 90% interval 0.73 to 1.02.
Homologues: Orthologues: macaque IFNL3 (93% identical), chimpanzee IFNL3 (92% identical), dog IFNL3 (72% identical), pig IL28B (68% identical), mouse Ifnl2 (63% identical), mouse Ifnl3 (60% identical), tropical clawed frog ifnl3 (24% identical), tropical clawed frog ifnl3.4 (23% identical), tropical clawed frog ifnl2 (22% identical). Paralogues in human: IFNL3 (94% identical), IFNL1 (70% identical).
Diseases named in the same sentence as IFNL2 in open-access papers:
IFNL2 is named in the same sentence as 62 diseases in open-access papers, as found by Europe PMC text mining. Sharing a sentence is not in itself a finding about the gene and the disease. The quoted sentences say what the papers report.
viral infection (13 papers, 2010 to 2025). "Next, we compared the top 10 upregulated cytokines/chemokines and found strong upregulation of IFNL2/3, IL-6, and IFNB1 in all animals with severe yellow fever." (PMID 40663406, 2025). "Meanwhile, the absence at Cys44 of ATG10S makes it possible for its nuclear translocation and combination with interferon lambda 2 (IL28A), which mediate the clearance of viral infections through autophagy." (PMID 37398657, 2023).
COVID-19 (7 papers, 2021 to 2024). A disease caused by infection with severe acute respiratory syndrome coronavirus 2. "Lower IFNL2 was also associated with a more severe clinical outcome in COVID-19 patients with significantly reduced levels in patients with severe disease (WHO 5–8) compared to a milder outcome (WHO 1–2)." (PMID 38953458, 2024). "Finally, we investigated if IFNL1 or IFNL2 levels were associated with disease severity in COVID-19 patients using good (WHO 1–2), mild (WHO 3–4), and bad (WHO 5–8) clinical outcomes to stratify the large cohort of Irish patients (n = 399)." (PMID 38953458, 2024). "While only IFNL3 had significantly higher levels of cytokine compared to HCV + patients, both IFNL1 and IFNL2 were significantly higher in COVID-19 patients compared to healthy controls." (PMID 38953458, 2024). "Moreover, expression of type I and III IFN genes in our oropharyngeal samples were measured, and increased IFNL2 mRNA levels in mild COVID-19 patients as compared to uninfected controls were found." (PMID 39085233, 2024). "Indeed, we found qualitative and quantitative differences in terms of frequency of induction, amount of cytokine produced and associations with severe COVID-19 outcome among IFNL1, IFNL2, and IFNL3." (PMID 38953458, 2024). "Both IFNL1 and IFNL2 levels were consistently low in patients with most severe COVID-19 (WHO 5–8)." (PMID 38953458, 2024). "Performing a similar analysis on the 75 COVID-19 patients with no plasma IFNL2 detectable, there was a clear association between worse outcome and absence of IFNL2 with 11 of the 20 patients who died (55%) having no detectable IFNL1 compared to 25% of the overall cohort." (PMID 38953458, 2024). "IFNL3 was induced in 95% of COVID-19 patients and at higher median levels compared to the IFNL1 or IFNL2." (PMID 38953458, 2024). "IFNL2 had quite a different profile with roughly similar frequencies of healthy controls (48.6%) and HCV + plasma samples (53.8%) having detectable levels of this cytokine; this increased to 75% of the COVID-19 patients." (PMID 38953458, 2024). "In this study, we measured all three IFNL1, IFNL2, and IFNL3 cytokines in plasma from a well characterized, large COVID-19 cohort (n = 399) that included good representation from patients with a more indolent disease progression, and hence a beneficial immune response." (PMID 38953458, 2024). "It was striking to note that a complete absence of either IFNL1 or IFNL2 occurred more frequently with more severe COVID-19." (PMID 38953458, 2024). "We did not detect changes in IFNL2,3, IFNL1, and IFNB1 expression, in agreement with reports of low IFN induction by SARS-CoV-2 infection and the role of several SARS-CoV-2 proteins as IFN-antagonists to limit antiviral response." (PMID 34446714, 2021).
Lipedema (6 papers, 2021 to 2025). Disorder of adipose tissue characterized by symmetric and bilateral enlargement of the lower extremities due to abnormal deposition of subcutaneous fat often in obese women. "The comparison between lipedema and control patients (pre-operatively) revealed significantly increased IL-11, interferon type III family IL 29 (interferon lambda 1) and IL28A (interferon lambda 2) levels." (PMID 33805070, 2021).
chronic hepatitis C (4 papers, 2011 to 2021). "To better understand the dynamics between type I and III IFNs expression in chronic hepatitis C patients, we also quantified the expression of IFNA1, IFNL1, IFNL2, IFNL3 and IFNL4 in 24 healthy volunteers." (PMID 34307188, 2021). "A previous analysis of hepatic IFNL2/IFNL3 transcripts in chronic hepatitis C patients was carried out covering them both and did not reveal any induction by chronic HCV infection in patient livers." (PMID 26606750, 2015).
asthma (3 papers, 2015 to 2023). "As expected, it blocked expression of IFNL2/3 (IFN-λ) in HBECs of patients with asthma and subsequently decreased expression of DDX58 (RIG-I)." (PMID 37087523, 2023).
hepatitis C (3 papers, 2012 to 2024). "The authors demonstrated slightly higher IFNL2/IFNL3 mRNA expression in the liver of hepatitis C patients carrying the minor non-favorable IFNL4 rs12979860 C alleles." (PMID 26606750, 2015).
influenza (2 papers, 2013 to 2024). An acute viral infection of the respiratory tract, occurring in isolated cases, in epidemics, or in pandemics; it is caused by serologically different strains of viruses (influenzaviruses) designated A, B, and C, has a 3-day incubation period, and usually lasts for 3 to 10 days. "We next assessed expression levels of various cytokines and chemokines (i.e., IFNB1, IFNL1, IFNL2/3, IFIT1, IFIT3, OAS1, MX1, IL‐6, CXCL10, and IFITM1) which were triggered by influenza and OC43 virus infections alone or together by qPCR." (PMID 38556468, 2024).
lupus (2 papers, 2022 to 2024). "Elevated blood levels of IFNλ3, as well as increased IFNL2 and IFNL3 mRNA have been detected in blood CD4+ T cells of lupus-prone mice and patients." (PMID 35833127, 2022).
ZIKV infection (2 papers, 2021 to 2023). "Here we showed the augmented compartmentalized expression of type III interferons (IFNL2) during ZIKV infection." (PMID 34899713, 2021). "Moreover, a CRISPR activation screen recognized that IFI6 and other ISGs, including Interferon Lambda 2 (IFN-λ2), can rescue cells from ZIKV infection." (PMID 37891676, 2023).
Listeria infection (1 paper, 2021). "In contrast, 3-day Listeria infection, triggered the expression of IFNL1 (coding IFN-λ1) and, to a lesser extent, IFNB1 (coding IFN-β) and IFNL2 (coding IFN-λ2) transcripts in HepG2 cells, while low levels of IFNB1 transcripts were detected in infected PMH." (PMID 34858876, 2021).
pulmonary tuberculosis (1 paper, 2017). A bacterial infection that affects the lungs and is caused by Mycobacterium tuberculosis. "In addition, the IFNL2 concentration in sputum of patients with pulmonary tuberculosis is significantly higher than that in the sputum of healthy controls." (PMID 28293236, 2017).
reovirus infection (1 paper, 2015). "In IEC preparations from Ifnlr1-/- mice that are highly susceptible to reovirus infection, induction of the Ifnl2/3 genes was nearly 100-fold higher than in infected wild-type mice, whereas type I IFN genes were not expressed at enhanced rates at this early time point." (PMID 25849543, 2015).
rheumatoid arthritis (1 paper, 2021). A chronic, systemic autoimmune disorder characterized by inflammation in the synovial membranes and articular surfaces. "In contrast, in a mouse model of rheumatoid arthritis, treatment with IFNL2 prevented arthritis progression, resolved inflammation, and improved pathology in comparison to a vehicle treated group." (PMID 34899712, 2021). "IFNL protein levels are upregulated in the sera of patients with rheumatoid arthritis compared with healthy controls; more specifically IFNL1 and IFNL2 levels are upregulated in patients with active disease." (PMID 34899712, 2021).
ulcer (1 paper, 2021). "Transcriptional analysis of biopsy tissue indicated that type II interferon, IFNG, not type I (IFNA4 and IFNB1) nor type III (IFNL1, IFNL2, IFNL3) interferons, was the prevalent interferon gene detected in ulcer lesions and 8 weeks post-healed skin." (PMID 34552595, 2021).
infection (51 papers, 2010 to 2025). The state of being infected such as from the introduction of a foreign agent such as serum, vaccine, antigenic substance or organism. "Infection with RSV-HD resulted in decreased viral mRNA and infectious titers in the lungs on day 2 post infection that associated with strong expression of IFNβ and Ifnl2 detectable as early as 6 h post infection." (PMID 26336095, 2015). "Genes encoding interferons (Ifnb, Ifnl2 and Ifnl3), chemokines (Ccl7, Ccl5, and Cxcl10), and ISGs (Ifit1, Ifit2, Ifit3b, Oas3, Ifi44, Rsad2, and Isg15, among others) were prominently represented among those induced by infection in Ifnar1-/- mice." (PMID 34591933, 2021). "In our study, patients with mild COVID had a rapid production of IFNL1 and IFNL2, which although decreasing over time, was still detectable 2 months post-infection." (PMID 38953458, 2024). "We observed that IFNL2 sharply increased to a 25-fold increase 10 h after infection and fell to 12-fold at 24.h." (PMID 37564646, 2023). "In PMH, quantification of Ifnb1, Ifnl2, and Ifnl3 transcript levels [murine Ifnl1 is a pseudogene] showed that infection elicited the expression of only Ifnb1, which was 40 times higher at 24 h than at 72 h p.i.." (PMID 34858876, 2021). "A first significant infection-dependent regulation was observed at 18 h, where Ifnl2 was detected in all DBA/2J and four of five C57BL/6J samples." (PMID 24341411, 2013). "Consistent with very low levels of infection, transcripts of immune mediators Il22 and Ifnl2/3, previously shown to be upregulated following robust RV infection, were not significantly increased in the infected Atoh1cKO intestine as compared to uninfected cKO littermates." (PMID 39727412, 2025). "Lambda interferons (IFNLs) include IFNL1/interleukin-29 (IL-29), IFNL2/IL‐28A, IFNL3/IL‐28B, and IFNL4, all of which are critical for a balanced antiviral response in the respiratory tract for optimal protection against infection and minimizing associated damage." (PMID 38703289, 2024). "MAYV infection alone resulted in a relatively modest increase (≈100-fold) in Ifnb and Ifnl2, which were further increased ≈10-fold by poly(I:C) challenge." (PMID 34944018, 2021). "In the brain, infection with Bov342 induced the expression of type-I (Ifna5, Ifnb), -II (Ifng), and -III (Ifnl2) interferons (IFN), interferon stimulated genes (ISGs) (Isg15, Ifit1, Mx1, Oas1), and pro-inflammatory cytokines (Il1b, Il6, and Tnfa) at endpoint." (PMID 40410375, 2025). "IFNB1 expression was also elevated following infection; however, IFNL1, IFNL2, and IFNL3 expression clearly dominated the innate immune response." (PMID 36268025, 2022). "At 24 and 48 h post-infection, the predominant interferons induced in the primary airway cells at the mRNA level were IFNβ, IFNL1, and IFNL2/IFNL3 (qRT-PCR cannot distinguish these isoforms), with IFNL1 and IFNL2/3 being the most upregulated." (PMID 34899695, 2021). "IFN-λ genes (IFNL1, IFNL2, IFNL3) were the most highly expressed among the interferon genes at both 12 and 24 h post-infection for all viruses." (PMID 32849329, 2020). "Infection-induced gene expression levels of inflammatory cytokines such as Il6 and Tnf, type I (Ifna4 and Ifnb), and type III IFNs (Ifnl2/3) as well as ISGs such as Mx1, Isg15, and Stat1 peaked simultaneously with peak viral loads on day 2 p.i. in lungs and upper airways." (PMID 36129445, 2022). "We observed increased IFNB1, IL29/IFNL1, IL28A/IFNL2, IFNL3, RSAD2, and CXCL10 post infection." (PMID 33409274, 2020). "S. epidermidis isolated from healthy individuals (N1, N2, N3, and N4) significantly elevated the levels of IFNL1 and IFNL2/3 mRNA in NHNE cells starting at 8 h after treatment, with maximum levels observed 24 h after infection (IFNL1 6.4 × 103, IFNL2/3 1.1 × 104)." (PMID 31146794, 2019). "Ifnl2/3 but not type I IFN genes were significantly induced in cells from wild-type mice on day 1 post infection." (PMID 25849543, 2015).
infection (continued). "This includes most Ifna isoforms, Ifnl2, Ifnl3, Ifnb1, Tnf, and numerous other chemokines and cytokines representing the acute pDC anti-viral response that is absent in suppressed pDCs at later stages of infection." (PMID 39920132, 2025). "Upon in vitro infection with ZIKVBR, a marked induction of mRNA expression of IFNB1, IFNL1, IFNL2 and IFNL3 genes but not of IFNE was observed." (PMID 32745093, 2020). "NAECs from control (no wheeze/no infant RSV infection) and RSV (no wheeze/RSV) children had increased IFNL2 gene and IFN-β protein expression after in vitro RSV 01-2/20 infection compared to NAECs from children with wheeze/no RSV infection and wheeze/RSV phenotypes." (PMID 40408478, 2025). "Upon infection, expression of IFNL1 and IFNL2 but not type I IFN in P. alecto." (PMID 39968756, 2025).
tumor (10 papers, 2005 to 2024). "Overall, our analysis showed that IFN-λ cancer-specific expression may be caused by copy number amplification of IFNL2 and IFNL3 in tumor patients, and most IFN-λ related genes also had copy number amplification and expression upregulation in BSE group." (PMID 37697300, 2023). "The results showed that endogenous IFN-λ expression may be mainly caused by copy number amplification of IFNL2 and IFNL3 genes in tumor patients." (PMID 37697300, 2023). "Moreover, IFN-λ specific expression may be caused by copy number amplification of IFNL2 and IFNL3 in tumor patients and driven cancer progression." (PMID 37697300, 2023). "Among the top genes differentially expressed between sensitive and resistant cells, we identified a group of candidates related to tumor-microenvironment response (CCL5, CXCL10, IFIT3, IFI44, IFNL2)." (PMID 32365528, 2020).
cancer (3 papers, 2022 to 2024). A tumor composed of atypical neoplastic, often pleomorphic cells that invade other tissues. "Thus, we stimulated each cancer cell line with HT-DNA and measured expression of IFNL1, IFNL2, and IFNB1 after 2, 6, 10 and 20 hours." (PMID 40012911, 2024).
IFNL2 also shares sentences with these, for which no sentence is quoted: hepatoma (4 papers); liver disease (4); brucellosis (2); lung carcinoma (2); Anxiety (1); autoimmune gastritis (1); Autoimmunity (1); bacterial infection (1); bladder cancer (1); breast carcinoma (1); cardiovascular diseases (1); cervical cancer (1); chronic hepatitis B (1); chronic rhinosinusitis (1); colitis (1); colon cancer (1); Crohn disease (1); depression (1); Down syndrome (1); echovirus infection (1); fibrosis (1); glioblastoma (1); glioma (1); glomerulonephritis (1); Immunodeficiency (1); inflammatory bowel disease (1); insomnia (1); Insulin resistance (1); Iron deficiency anemia (1); malaria (1).
A further 15 diseases each share a sentence with IFNL2 in 1 paper.